VAV2 (vav guanine nucleotide exchange factor 2)
Diseases named in the same sentence as VAV2 in open-access papers (continued):
Sharing a sentence is not in itself a finding about the gene and the disease.
cancer (36 papers, 2010 to 2025). A tumor composed of atypical neoplastic, often pleomorphic cells that invade other tissues. "Aberrant VAV2 expression or mutations are implicated in the pathogenesis of various diseases, particularly cancer." (PMID 40303312, 2025). "The deregulation of VAV2 expression or activity has been associated with cancer, autoimmune and neurological disorders." (PMID 39744818, 2025). "Other genes from this list are linked to various types of cancer (Pnck, Calu, Vav2, Kif3a, Adgrf5, N4bp2l2)." (PMID 32467583, 2020). "High expression of Vav2 is implicated in cancers such as oral squamous cell carcinoma, squamous carcinomas of the head and neck, and prostate cancer." (PMID 26353933, 2015). "Furthermore, several GEFs including PREX1 and Vav2 as well as Vav3 are reported to be over-expressed and associated with carcinoma progression." (PMID 29454349, 2018). "Carcinomas from Vav2;Vav3-deficient mice also displayed up-regulation of the Hgf mRNA." (PMID 23935450, 2013). "VAV2 has been reported to play a pivotal role in drug resistance, invasion, metastasis, and maintenance of cancer stem cells." (PMID 40518514, 2025). "VAV2 overexpression has been observed in breast, colon, lung and other cancers, where it promotes cell proliferation, invasion and metastasis." (PMID 39744818, 2025). "It is well known that Vav2 is also overexpressed in most human cancers and promotes cancer cell migration and invasion in several types of human cancer." (PMID 35882892, 2022). "Grb2 not only activated Ras pathway signaling to regulate cancer cells growth, but also interacted with Vav2 to activate Rac1 pathway signaling." (PMID 36268019, 2022). "We discovered that cortactin phosphorylated at Y-470 recruits the signaling factor Vav2 to activate the small Rho GTPase Rac1, and finally, a cancer cell motility phenotype." (PMID 34439396, 2021). "By analyzing the TCGA data using gene expression profiling interactive analysis, we found that VAV2 is overexpressed in most types of cancer compared with normal tissues, indicating that VAV2 is a featured oncogene." (PMID 34462423, 2021). "According to our data, this therapeutic response will probably be stronger in cancer cells exhibiting high levels of VAV2 activity." (PMID 32899210, 2020). "Outside of the hematopoietic system, VAV2 is critical for regulating tumorigenesis and cancer progression." (PMID 32353968, 2020). "This expression is concentrated in the cancer cells rather than in the surrounding stromal components, further demonstrating that the upregulation of VAV2 is a cancer cell-intrinsic phenomenon." (PMID 32963234, 2020). "The results revealed that the mutation frequencies of both VAV2 and IQGAP1 are higher in HNSCCs than in any other cancer types." (PMID 31798960, 2019). "To determine if the susceptibility genes identified in the OSCC family are associated with HNSCCs, we screened the ICGC dataset and analyzed the mutation frequencies of VAV2 and IQGAP1 in different cancer tissues derived from 19 different anatomic sites." (PMID 31798960, 2019). "Like Vav1, Vav2 and Vav3 become oncogenic following N-terminal truncation, yet there appears to be Vav isoform-distinct functions in cancer." (PMID 26353933, 2015). "In doing so, we further uncover the signalling mechanisms driving EphA-mediated cell–cell repulsion and find that signalling from EphA receptors, via the guanine nucleotide exchange factor (GEF) Vav2 to activate RhoA, can stimulate cancer cell–cell repulsion." (PMID 24795148, 2014). "Consistent with the finding that CIL drives embryonic cell dispersal during development, we show here that EphA receptors mediate CIL via Vav2 and RhoA and that EphA2/EphA4 can regulate cancer cell dissemination from dense cancer cell populations." (PMID 24795148, 2014).
cancer (continued). "Finally, we investigated whether the tumors that developed in Vav2;Vav3-deficient mice could be the result of the outgrowth of cancer cells that, due to selection events, could have compensated the lack of Vav proteins by the exacerbation of other signaling routes." (PMID 23935450, 2013). "Vav2 is important in mediating cytotoxic lymphocyte activity against target cells including cancer cells, but studies in epithelial cells using siRNA knock-down of Vav2 suggest an important role in stimulating cell migration." (PMID 20624275, 2010). "Moreover, the data obtained with SCC-25 cells suggest that, in some cases, the proliferative and ribogenic activity of cancer cells can independently be regulated by VAV2-dependent and independent pathways, respectively." (PMID 38374399, 2024). "Vav2 is broadly expressed in human tissues and is involved in regulating various biological processes, including cell spreading and migration, neuronal development, angiogenesis, and cancer cell motility." (PMID 35882892, 2022). "Vav2 had been reported to upregulate cell motility by promoting the cycling between an inactive Rac1-GDP-bound state to an active Rac1-GTP-bound state in many cancer types." (PMID 35177591, 2022). "Overall, our current study has substantiated the critical roles of Rac1 in Hh signaling transduction, and the Hh-Vav2-Rac1-PAK1 pathway may provide additional therapeutic targets for cancer cells of Hh activation." (PMID 35154488, 2022). "Recurrent VAV2 overexpression may reflect the cellular response to the oncogenic genome alterations in cancer cells." (PMID 34462423, 2021). "Moreover, Vav2/3 overexpression and activation has been reported from multiple cancers, including metastatic melanoma, endometrial, cervical, breast, and prostate cancer." (PMID 32322580, 2020). "Perhaps more importantly, we have observed that the elimination of endogenous VAV2 eliminates the tumorigenic potential of hnSCC patient-derived cells and standard hnSCC cancer cell lines using both orthotopic xenotransplants in vivo and 3D organotypic cultures." (PMID 32899210, 2020). "Vav2 and Vav3 homologs are expressed in non-hematopoietic tissues and have been implicated with cardiovascular diseases and cancer." (PMID 32322580, 2020). "Thus, we performed KEGG pathway analysis on the candidate genes and found that IQGAP1 and VAV2 were both enriched in the “Proteoglycans in Cancer” pathway (hsa05205)." (PMID 31798960, 2019). "The Vav2 protein acts downstream of a myriad of cell surface receptors, many of which are overexpressed already in precancers and therefore may activate Vav2 to drive cancer progression." (PMID 25785189, 2014). "Furthermore, Vav2 has been deemed a promising target for cancer therapy, with small molecule compounds being developed that specifically target Vav2 activity in cancer." (PMID 25785189, 2014). "Similarly, KCC4, a closely related cotransporter that also harbors the proline-rich region capable of interaction with Vav2, has an important role in cancer cell invasion and metastasis as well." (PMID 23724134, 2013). "However, whether Vav2-Rac1 may exert their pleiotropic effects on cancer cells treated with CCL2 as a complex remains unclear." (PMID 35177591, 2022). "Several studies also indicated the involvement of VAV2 in RAC activation and cancer motility by functioning as RAC guanine exchange factor (GEF) to convert inactive RAC-GDP to the active RAC-GTP." (PMID 39527598, 2024). "We found that three pathways, “Pathways in cancer” (hsa05200), “Focal adhesion” (hsa04510), and “Insulin signaling pathway” (hsa04910), are widely affected by IQGAP1 and VAV2." (PMID 31798960, 2019). "Despite the apparent limitation of our study DCIS cohort size, our novel findings on Vav2 hold promise for utilizing Vav2 protein as a BM of progressive DCIS and a target for cancer therapy." (PMID 25785189, 2014).
cancer (continued). "We selected potential miR-148a cancer-related target genes, namely ITGA11, ITGB8, VAV2, ROCK1 and WASL, which are known to be involved in integrin pathway-promoting cell migration, motility, actin polymerization, and cytoskeleton remodeling." (PMID 25277193, 2014). "Similarly, miR-195 has been shown to impede angiogenesis by targeting proteins such as VEGF, Vav guanine-nucleotide exchange factor 2 (VAV2), and cell division cycle 42 (CDC42), ubiquitously involved in cancer progression, including HCC." (PMID 37958352, 2023). "Although VAV2 inhibitor is currently unavailable, the STAT1 signaling pathway is druggable and may serve as an alternative target for reversing radioresistance of cancer cells." (PMID 34462423, 2021). "It has been shown that genomic structural alterations such as chromothripsis, a pervasive event across cancers, can induce DNA NHEJ repair, which may mechanistically require VAV2 upregulation." (PMID 34462423, 2021). "Therefore, the identification of the interaction between Vav2 and APP may open up a novel avenue for further research on the role of APP in cancer." (PMID 35882892, 2022). "Moreover, CO-IP and confocal microscopy results revealed that the binding of Vav2 and Rac1 was enhanced in cancer cells following treatment with CCL2, which indicated that CCL2 induces the functional coupling of Vav2 and Rac1 and the formation of the Vav2-Rac1 molecular complex." (PMID 35177591, 2022). "Therefore, VAV2 expression level might serve as a biomarker for predicting radiosensitivity of ESCC and perhaps some other types of cancer in view of the results we have obtained from the pan-cancer analysis." (PMID 34462423, 2021). "Therefore, we suggest that EphA2 and EphA4 can signal via Vav2 and RhoA leading to microtubule destabilisation and subsequently cell–cell repulsion, although we cannot rule out additional signalling events regulating cancer cell repulsion downstream of EphA receptors." (PMID 24795148, 2014). "At the same time, IHC staining in transplanted tumors indicated that the CCR4 antagonist could effectively downregulate the phosphorylation of Vav2 and MLC in cancer cells, but not in tumors treated with CCL2 neutralizing antibody." (PMID 35177591, 2022).
infection (7 papers, 2008 to 2024). The state of being infected such as from the introduction of a foreign agent such as serum, vaccine, antigenic substance or organism. "An important gene for growth during stress, CHORDC1 associated with post-infection growth rate was identified as a positional candidate gene, as well as other immune related genes, including VAV2, IL12B, DUSP1, and IL17B." (PMID 32849779, 2020). "As the next step, we aimed to study if the expression of cortactin and Vav2 were required for the activation of Rac1 during infection." (PMID 34439396, 2021). "First, to identify if Vav2 is also involved in host cell invasion by C. jejuni, the expression of Vav2 was suppressed with siRNA, followed by infection and gentamicin protection assays." (PMID 22204307, 2011). "Next we aimed to consolidate our understanding of the potential importance and role of Vav2 during infection." (PMID 22204307, 2011). "L2 infection of HeLa cells induced tyrosine phosphorylation of WAVE2, Vav2, and Cortactin at 1 hour post infection (lane 2)." (PMID 18369471, 2008). "In contrast, infection of AGS cells transfected with siRNAs, interfering with cortactin, Vav2 or Rac1 expression exhibited strongly reduced wound healing activities." (PMID 34439396, 2021). "As expected from existing RNAseq data, Vav2 is a major Vav present in ARPE-19 cells but was not affected at mRNA or protein level by DENV-infection." (PMID 38054722, 2024). "The importance of Vav2 was then confirmed by the expression of dominant-negative constructs and the use of Vav1/2 knockout cells in infection assays." (PMID 22204307, 2011).
VAV2 also shares sentences with these, for which no sentence is quoted: colorectal cancer (3 papers); hyperglycaemia (2); leukemia (2); type 2 diabetes (2); Adrenal Tumours (1); anaplastic large cell lymphoma (1); arterial embolism (1); cardiovascular disease (1); ductal carcinoma in situ (1); epilepsy (1); fibrosis (1); fungal infections (1); glioblastoma (1); hepatocellular carcinoma (1); laryngeal squamous cell carcinoma (1); liver cancer (1); myopia (1); Obesity (1); open-angle glaucoma (1); prostatic adenocarcinoma (1); renal cell carcinoma (1); retinopathy (1); T-cell lymphoma (1); thrombosis (1); thyroid papillary carcinoma (1); triple-negative breast carcinoma (1).